CD4 (CD4 molecule)
Diseases named in the same sentence as CD4 in open-access papers (continued):
Sharing a sentence is not in itself a finding about the gene and the disease.
infection (continued). "In our modelling we observed that if G+ CD4+T cells only exhibited reduced likelihood of productive infection (i.e. under standard scenario STD), then limited persistence/expansion of G+ CD4+T cells and little therapeutic impact was achieved with one-off delivery of therapy to CD4+T cells." (PMID 24945407, 2014). "Several groups have shown that during L. major infection, CD4+CD25+ Treg cells accumulate at the primary infection site in both humans and mice where they suppress parasite elimination by CD4+CD25− effector cells and mediate chronicity, and their depletion leads to parasite clearance." (PMID 25104882, 2014). "The distribution of CD4 in macrophages may influence the site of fusion of the virus envelope with a cell-limiting membrane, and therefore directly impact the efficiency of infection." (PMID 24465876, 2014). "C8166 cells express CD4 and CXCR4 and are therefore susceptible to infection by NL4.3, IIIB and HE." (PMID 25499264, 2014). "Our current results provide a system to test whether the magnitude of antigen specific CD4+ T cells is an important factor for vaccine efficacy in the control of M.tb. either for prevention of infection or limitation of active disease." (PMID 24404140, 2014). "Several miRNAs correlate with CD4+ T cell count or with the known time of infection." (PMID 25081906, 2014). "Interestingly, vaccinees M770F and BD765B, which had a high peak viremia (2.1×105 and 9.4×104 RNA Eq/ml, respectively) and remained viremic in the chronic phase of infection, exhibited a very divergent dynamics with regard to the CD4+ T cells counts." (PMID 25356594, 2014). "HIV-1 trans-infection involves capture and internalization of intact virions by DCs, trafficking of trapped viruses without membrane fusion, and finally release of infectious virions towards contacting CD4+ T cells." (PMID 25033082, 2014). "Thus, infection with Ad5hr induced a complex pattern of innate and adaptive immunity in RM that included transient systemic CD4+ T cell activation and suppressed innate immunity on re-exposure to the virus." (PMID 25203111, 2014). "Plasmodium species have different stages with different tissue tropisms and this complex life cycle challenges the idea that a single static group of terminally differentiated CD4+ T-cells would be able to perform all the tasks required to control this infection." (PMID 25628621, 2014). "Given that the survival of 2W1S-specific memory T cells was not significantly impaired by anti-OX40L Abs, expression of OX40 by 2W1S-specific CD4+ T cells during the response to Lm-2W infection was assessed, with total CD4+ Treg cells used as a positive control for OX40 detection." (PMID 24771127, 2014). "Lipid accumulation and modulated activation in pDCs and CD4-CD8α+ DCs may contribute to the declining responses to vaccination and infection with age." (PMID 25089147, 2014). "By day 7 after infection, the eYFP signal was more restricted to CD4+ T cells and myeloid cells." (PMID 24825601, 2014). "During the PE period, the levels of activated CD4+ and CD8α+ cells in vaccinated pigs were significantly higher than in controls during the first weeks before infection (15-17 weeks); these subsets were mainly constituted of naïve and memory T helper cells able to respond to PCV2." (PMID 24735253, 2014). "Finally, the silent and severe infection groups had higher levels of IL-17+CD4+ and IL-17+CD8+ cells at the CP relative to their levels at baseline and relative to those in the control and minor infection groups." (PMID 24646014, 2014). "Our results are compatible with a scenario where CD8+ T-cell responses are strictly focused on infected tissue compartments, whereas CD4+ responses may induce a more regional state of antimicrobial protection in tissues surrounding infection foci." (PMID 25121482, 2014).
infection (continued). "These mice exhibited increased numbers of parasite-specific CD4 T cells that produced IFN-γ at the infection site and draining lymph node and were protected from reinfection, suggesting again that interfering with T cell death may boost vaccine efficiency." (PMID 24551250, 2014). "Importantly, NOD-1/NOD-2 deficiency did not alter IL-17A production during the late “adaptive” phase of infection suggesting that these sensors specifically regulate early CD4+-T-cell-derived IL-17." (PMID 24586147, 2014). "In other words, the higher polyfunctional responses observed in these subjects coupled with a larger number of CD4+ T cells during early infection may ultimately result in an overall slower in vivo replication rate of the virus." (PMID 25187947, 2014). "Stat-6−/− and CD4-TGFβRIIDN animals individually showed partial resistance to infection." (PMID 24711459, 2014). "CD4 T cells progressively accumulated inside follicles as acute infection progressed." (PMID 24763747, 2014). "The ratio between Th1, Thpp and Tfh differentiation may be regulated by the inflammatory environment during infection, but may also be affected by the individual properties of different naïve CD4 T cells, such as TCR affinity." (PMID 24788814, 2014). "In contrast, CD4+ depleted mice along with MVA-GFP controls succumbed to infection." (PMID 25058320, 2014). "This remarkably broad distribution echoes the diverse functions of CD4+ TEFF cells in infection control, ranging from the initiation of antibody class-switching in LNs to the regulation of inflammatory cell infiltration and activity as well as direct antimicrobial effects within infected tissues." (PMID 25121482, 2014). "Importantly, interfering with CD28 costimulatory signalling before re-infection impaired the recruitment and/or expansion of central and effector memory CD4+ T cells and follicular B cells to the draining lymph node of tamoxifen treated CD28−/loxCre+/− mice." (PMID 24516382, 2014). "A decrease in IFN-γ production has also been shown upon infection of primary CD4+ cells with HCV." (PMID 24465502, 2014). "However, whereas control animals showed a rapid drop in viral load after the peak, CD4-depleted animals maintained viremia close to peak levels and ∼2-logs higher than controls in later infection." (PMID 25356757, 2014). "These include the role of CD8+ T cells in viral clearance and immunopathology, the importance of CD8+ T cells in influencing CD4+ T cell function, and the influence of vaccine priming and allergic inflammation on CD4+ T cell differentiation and pathology post-infection." (PMID 24897427, 2014). "Since defects in NK immune surveillance may also impair the anti-infectious immunity, they could also partly explain the susceptibility to infection of HIV patients during chemotherapy, even in patients with high CD4+ T-lymphocytes levels." (PMID 25908934, 2014). "We therefore asked whether IL-10 produced by CD4 T cells contributed to increased infection with S. Typhimurium." (PMID 24787713, 2014). "However, the early control viral gene transcription in C57BL/6 mice at week 1–2, that is maintained in the CD8 KO mice but lost in the CD4 KO mice, strongly suggests that CD4-mediated innate immune responses also plays a role in controlling infection." (PMID 25121947, 2014). "To assess the effect of Ad5hr infection on CD4+ regulatory T cells, we evaluated the frequency of CD4+ Treg (Foxp3+/CD25hi) and a CD4+ Treg subset expressing CTLA4 (Foxp3+/CTLA4+/CD25hi) that is thought to be particularly immunosuppressive, as CTLA4 is required for suppression by Tregs." (PMID 25203111, 2014). "CD4 TRM in mucosal tissues may be optimally poised to orchestrate the immune response to recurring tissue-tropic infections." (PMID 25071787, 2014).
infection (continued). "By the classical antigen presentation pathway or by the cross-presentation pathway, any form of virus can be presented on MHC class I and MHC class II and thereby stimulate antiviral responses by both CD8+ T cells and CD4+ T cells, respectively, leading to a broad cellular response to infection." (PMID 24795718, 2014). "Infection of a CD4 T cell by HIV results in one of three outcomes." (PMID 26056587, 2014). "Studies have shown that patients with CD4 cell counts < 300 cell/μl are at high risk of re-infection rather than recrudescence when treated with AL." (PMID 24885714, 2014). "We hypothesized that the efficiency of MDM infection by HIV-1+ CD4+ T cell uptake might influence viral tropism, and we used ImageStream to investigate the fate of macrophage (M)-tropic and nonmacrophage (NM)-tropic HIV-1-infected T cells associated with MDM." (PMID 25467409, 2014). "A consistent reduction in CD4+ T cells was observed at 4 days post infection (dpi)." (PMID 24559207, 2014). "Infection of a rare CD4+ T cell with very high ICRN could thus be the superspreading event that both establishes HIV infection in the genital mucosa and selects a single founder strain." (PMID 24811311, 2014). "The studies showed that cytokines that are present at the site of infection can influence the direction of naïve CD4 T cell differentiation, and therefore may determine the shift in the effector dominance." (PMID 24415928, 2014). "Together, these data suggest that upon infection with HIV the majority of CD4+ T cells in the genital mucosa would spread the virus to few if any others and that only rare cells would have the capacity to release large quantities of HIV to their nearest neighbors." (PMID 24811311, 2014). "Finally, elimination of infection resulted in significantly decreased frequencies of antigen – specific CD4+ T cells expressing IL-10, IL-19 and IL-24." (PMID 24699268, 2014). "Since the gut mucosal homing receptor α4β7-integrin binds to HIV-1 and might be important for productive infection of CD4+ T cells, we next investigated whether GPR15 positive lymphocytes co-express gut (α4β7-integrin) and lymph node (CD62L) homing receptors." (PMID 24558379, 2014). "Based on the paucity of CD4+ T-cells and the infection of macrophages/myeloid cells, which are typically thought to be long-lived cells, we hypothesized that in CD4-depleted RMs viral load decay during ART would be slower when compared to undepleted controls." (PMID 25356757, 2014). "In Italian HIV patients, serum LPS levels predicted disease progression independently of age, CD4+ T-cell count, viral load, or duration of infection, and higher circulating LPS levels after ART initiation were associated with greater CD4+ and CD8+ T-cell activation and poor CD4+ T-cell recovery." (PMID 25266928, 2014). "The hierarchy of CD4 helper T cell epitopes was preserved during secondary infection years later." (PMID 24982656, 2014). "We conclude that on co-culture of CD4+ T cells with autologous MDMs, T cell association with MDMs precedes VS formation, which in turn precedes the efficient MDM to T cell transfer of HIV, and T cell infection." (PMID 24991932, 2014). "Thus, latently infected cells carrying WT virus were laid down early in infection, and measuring the persistence of WT DNA in resting CD4+ T cells tells us about the duration of SIV latency." (PMID 24710023, 2014). "It is possible that durable T-cell-mediated control of infection, which would require continuous renewal of effective HIV-specific CD4 and CD8 T cells, may cause an exhaustion of hematopoietic progenitor cells in some ECs." (PMID 24465584, 2014). "In conclusion, under the conditions of this study, the administration of a PCV2 subunit vaccine induced a long-lasting immunity sustained by reactive CD4+CD8+ memory T cells and IFN-γ secreting cells, which were associated with the prevention or reduction of infection and clinical signs." (PMID 24735253, 2014).
infection (continued). "Importantly however, the frequency of CD4+ T cells was restored to essentially pre-infection levels in this site (47.2±0.4%) by the end of cART." (PMID 25033210, 2014). "We also show a CD4+ IL-17 response to infection, and the production of several other cytokines." (PMID 24615129, 2014). "Foxp3+ Treg were identified as CD4+GFP+ lymphocytes at different time points during infection." (PMID 24516385, 2014). "Furthermore, resting CD4+ T cells did not produce CXCL10 in response to Sendai virus infection, whereas the IL2/PHA-activated CD4+ T cells responded to this infection in a manner similar to the IL2/PHA-activated PBMCs." (PMID 24404168, 2014). "Whether the size of the latent reservoir is determined early in infection or is related to peak viral loads or CD4/CD8 ratio is currently debatable." (PMID 25486977, 2014). "A type I IFN resistant phenotype could be essential for robust viral replication during the acute stage of infection, depletion CD4 T-cells, and suppression of CD4 helper T-cell dependent responses." (PMID 25256394, 2014). "This type of vaccine it is not expected to protect from infection acquisition, but rather to contain infection (i.e., low to undetectable plasma viral load and no CD4+ T cell loss), preventing progression to disease as well as virus transmission." (PMID 25250026, 2014). "Our initial data point to the Th cell compartment as the main cellular source of IL-4 and IL-13 early in the infection as revealed by analysis of IL-4 and IL-13 mRNA expression in the enriched pulmonary CD4+ population of WT mice (our own unpublished observation)." (PMID 24475277, 2014). "Indeed, massive memory CD4+ T cell death due to direct infection and bystander cell apoptosis has been reported." (PMID 24558379, 2014). "Infection by both viruses was sensitive to increases in both CD4 and CCR5 expression levels." (PMID 24656066, 2014). "The affinity of Ad5 for long-lived antigen presenting cells, macrophages and DC in mucosal sites may partially explain the ability of these infections to suppress innate immunity and induce systemic CD4+ T cell activation." (PMID 25203111, 2014). "Virus expressing mainly p8 (N26), has an intermediate phenotype; it maintains its infectiousness for monocytes and CD4+ T-cells, but because it only partially protects infected CD4+ T-cells from CTL does not cause a robust infection in vivo." (PMID 25375128, 2014). "Rather the majority of Tregs may serve a role in inhibiting viral replication in other target CD4 T cells during early infection, which may assist in preventing the initial spread of the virus from the mucosal sites to lymph nodes." (PMID 25610441, 2014). "However, HIV-1 changes its co-receptor usage from CCR5 to CXCR4 only after many years of infection and this receptor change represents a switch to non-CD4-dependent platelet activation at late stages of disease." (PMID 25566260, 2014). "On the other hand, CD4+ T-cells are key targets for infection and sustain virus replication." (PMID 25356757, 2014). "Here we found that when compared to PP HIV-infected individuals, VNPs showed decreased infection of central memory CD4+ T cells (TCM) and stem cell memory T cells (TSCM) by HIV, as well as increased proliferation of memory CD4+ T cells, which was associated with increased CD4+ TCM counts." (PMID 25167059, 2014). "We observed both IL-9 producing CD4+ and CD4− cells during infection at very low frequencies." (PMID 24516385, 2014). "Before infection, individuals have on average 1,000 CD4+ T cells per μl of blood." (PMID 25226169, 2014). "There were significantly more CD38+ cells in the minor and severe infection groups than in the healthy and silent infection groups among CD8+ cells (CD4+: 5.13 and 9.14 vs. 1.67 and 2.49, respectively, p < 0.001; CD8+: 4.28 and 12.90 vs. 1.03 and 0.75, respectively, p < 0.001)." (PMID 24646014, 2014).
infection (continued). "Tregs may be divided into natural Tregs, which originate in the thymic medulla and induce regulatory T cells and adaptive Tregs, which arise from CD4+ T cells when infection, transplantation or cancer occurs." (PMID 24270972, 2014). "Evidence from Gondek and colleagues support this, whereby they demonstrated that infection of the upper genital tract with C. trachomatis induces a robust Chlamydia-specific CD4+ T cell response that is both necessary and sufficient to clear infection and provide protection against re-infection." (PMID 25386180, 2014). "Furthermore, since MCMV infection primarily induces stronger CD8+ T cell responses, the contribution of the enhanced CD4+ T cell activation we observe upon infection in Treg depleted mice would require further investigation." (PMID 25108672, 2014). "We show that primary monocyte-derived macrophages (MDMs) selectively capture autologous primary HIV-1-infected CD4+ T cells, leading to infection of MDMs that is of greater magnitude than the corresponding cell-free virus infection, particularly for T/F viruses." (PMID 25467409, 2014). "In rhesus macaques infected with L. infantum, the percentage of CD4 T cells in the spleen was significantly increased 11 days after infection (P<0.05), which resulted in a 3-fold increase in their total numbers that were thereafter maintained at constant levels." (PMID 24763747, 2014). "Using an epidemiological framework, we suggest that such heterogeneity among CD4+ T cells in the genital mucosa could help explain the low infection-to-exposure ratio and selection of the founder strain after sexual exposure to HIV." (PMID 24811311, 2014). "VP1 became detectable in CD4+ or CD8+ from wild-type mice as early as 12 h after infection." (PMID 24816846, 2014). "Thus, the generation of autoreactive responses, which included the generation of activated CD4 T cells and the production of antibody, following an acute infection, would often be sustained." (PMID 24684567, 2014). "Especially during acute HIV infection, regulatory T cells (Tregs) are upregulated, but HIV can target CD4+ Treg cells for infection, and Treg cells can suppress ant-HIV immunity, which may together promote an increase in acute viremia and infected cells." (PMID 25160905, 2014). "Interestingly, at a later time point, CD4+CD25+CD127low/− iTreg cells contribute towards the enhanced suppression of effector cells in SbR-LD infection by generating more IL-10 and TGF-β." (PMID 25032977, 2014). "SIV-infected rhesus macaques have revealed key aspects of HIV-1 pathogenesis, such as virus transmission, early post-infection events, the sites of viral replication, CD4+ T cell depletion, and virus and cell turnover, and these animals have been utilized in studies of viral reservoirs." (PMID 25487036, 2014). "Despite these findings, the role of infected cells in presenting antigen to CD4+ T cells in vivo during any infection remains unclear." (PMID 24722202, 2014). "HIV-1-specific CD4+ T cell responses are rapidly eliminated or dysfunctional early in infection in the majority of individuals and the HIV-1-specific CD8+ cytotoxic T cell (CTL) response develops functional abnormalities typical of T cell exhaustion during persistent viremia." (PMID 24586620, 2014). "In fact infection of susceptible, but not resistant mice with L. donovani induced apoptosis of splenic CD4+ T cells after in vitro stimulation." (PMID 25368612, 2014). "CD4+MIP-1β+ cells trended toward significance (P = 0.06) post-infection relative to pre-infection." (PMID 25397604, 2014). "In macrophages this is supported by plenty of evidence using recombinant soluble CD4 and anti-CD4 monoclonal antibodies, which block infection and ablate infection-related cytopathic effects by several macrophage-tropic HIV isolates, but this has not been tested genetically." (PMID 24465876, 2014).